MKRN2OS (MKRN2 opposite strand)
Synonyms: C3orf83; MKRN2-AS1
Tractability: No criterion of Open Targets' tractability assessment is met for any kind of drug.
Gene: Protein-coding gene on chromosome 3 (12,514,934 to 12,561,059, reverse strand). Ensembl gene ENSG00000225526.
Subcellular location (Human Protein Atlas): Golgi apparatus
Genetic constraint (gnomAD): Loss-of-function variants: 15 observed, 17.41 expected, observed/expected ratio (o/e) 0.86, 90% interval 0.57 to 1.33. The upper end of that interval is the gene's LOEUF score, 1.33, which puts it in group 5 of 6, group 1 being the genes least tolerant of losing a copy. Missense variants: 337 observed, 292.19 expected, observed/expected ratio (o/e) 1.15, 90% interval 1.05 to 1.26. Synonymous variants: 121 observed, 112.1 expected, observed/expected ratio (o/e) 1.08, 90% interval 0.93 to 1.25.
Homologues: Orthologues: chimpanzee MKRN2OS (98% identical), macaque MKRN2OS (94% identical), dog MKRN2OS (80% identical), pig MKRN2OS (74% identical), guinea pig MKRN2OS (72% identical), mouse Mkrn2os (69% identical), rat Mkrn2os (69% identical), rabbit MKRN2OS (53% identical), zebrafish mkrn2os.2 (45% identical), tropical clawed frog mkrn2os (44% identical).